RN7SL152P (RNA, 7SL, cytoplasmic 152, pseudogene)
Gene: Miscellaneous RNA gene on chromosome 4 (140,577,925 to 140,578,222, forward strand). Ensembl gene ENSG00000242102.
Homologues: Orthologues: chimpanzee Metazoa_SRP (99% identical), macaque Metazoa_SRP (95% identical). Paralogues in human: RN7SL1 (83% identical), RN7SL2 (83% identical), RN7SL3 (82% identical), RN7SL296P (80% identical), RN7SL126P (80% identical), RN7SL230P (80% identical), RN7SL408P (80% identical), RN7SL566P (79% identical), RN7SL778P (79% identical), RN7SL45P (79% identical), RN7SL664P (79% identical), RN7SL14P (78% identical), and 700 more.